NAIPP2 (NAIP pseudogene 2)
Synonyms: BIRC; NAIP1B
Gene: Transcribed unprocessed pseudogene on chromosome 5 (70,094,659 to 70,128,434, reverse strand). Ensembl gene ENSG00000179978.
Diseases named in the same sentence as NAIPP2 in open-access papers:
NAIPP2 is named in the same sentence as 10 diseases in open-access papers, as found by Europe PMC text mining. Sharing a sentence is not in itself a finding about the gene and the disease.
NAIPP2 shares sentences with these, for which no sentence is quoted: cancer (6 papers); triple-negative breast carcinoma (2); breast carcinoma (1); Cirrhosis (1); leukemia (1); lung adenocarcinoma (1); lung carcinoma (1); nasopharyngeal carcinoma (1); tumor (1); viral infection (1).